MACROH2A1 (macroH2A.1 histone)
Diseases named in the same sentence as MACROH2A1 in open-access papers (continued):
Sharing a sentence is not in itself a finding about the gene and the disease.
cancer (57 papers, 2013 to 2025). A tumor composed of atypical neoplastic, often pleomorphic cells that invade other tissues. "MacroH2A1 variants impact importantly the transcriptional regulation of tumorigenesis of many cancer types, notably gastrointestinal (GI) ones, as we and others have extensively reported." (PMID 37926763, 2023). "The H2AFY gene encodes for macroH2A1, a histone variant of the histone H2A that have been reported to be dysregulated in various human cancers." (PMID 34899687, 2021). "Along these lines, several other cancer-associated factors involved in splicing of macroH2A1 were identified." (PMID 34203934, 2021). "Previous studies aiming to dissect the specific cellular functions of the two splice variants of macroH2A1 were conducted in the pathophysiological context of cancer." (PMID 32365743, 2020). "While normal cells typically express both macroH2A1 variants, macroH2A1.1 expression is specifically lost in many cancers and functions as a tumor suppressor (20, –, 24)." (PMID 31636161, 2019). "MacroH2A1.1 is a histone H2A variant that negatively correlates with the self-renewal capacity of embryonic, adult, and cancer stem cells." (PMID 31439048, 2019). "MacroH2A1.1 is a potent transcriptional modulator associated with favorable outcomes in several solid tumor types, restriction of cancer stem-cell emergence, and PARP1 (Poly (ADP-ribose) Polymerase-1)-dependent chromatin remodeling." (PMID 31439048, 2019). "Among the naturally occurring sequences was a G4 from the 5′ untranslated region (UTR) of the H2AFY gene (also known as macroH2A1), encoding a histone variant involved in cellular differentiation and several types of cancer." (PMID 25510493, 2015). "MacroH2A1.1 and macroH2A2 inhibit proliferation and are associated with better cancer prognosis; while macroH2A1.2 is associated to cancer progression." (PMID 25003966, 2014). "The unique structure of the histone variant macroH2A1 may assist cancer cells in cell cycle regulation, as well as DNA repair and transcription." (PMID 38921460, 2024). "In this study, we focused on macroH2A1, an H2A variant, which is a transcriptional modulator that can either repress transcription or activate it in response to growth signals in somatic cells, stem cells, and cancer cells." (PMID 34356514, 2021). "MacroH2A1 is well known to regulate senescence onset, which is associated with cancer suppression." (PMID 31096699, 2019). "In support of this hypothesis, QKI has been considered a tumor suppressor in various cancers and frequently associated with MacroH2A1.1 downregulation." (PMID 31164793, 2019). "Given the well-established role of macroH2A1 as a barrier to reprogramming, and its association with cancer progression, we postulated that macroH2A1 may play a role in EMT, a process involving reprogramming of cellular states and an initiator of metastasis." (PMID 29339820, 2018). "Moreover, high levels of macroH2A1.1 are associated with slowly proliferating cancers, whereas highly proliferating tumors have markedly decreased macroH2A1.1 levels." (PMID 24911873, 2014). "Overall, these findings suggest that lower QKI and MacroH2A1.1 expression levels might be associated with worse PCa-related survival, a hypothesis that follows the same reported for other cancer models, but which requires further investigation in a larger cohort of PCa patients." (PMID 31164793, 2019). "To determine potential clinical relevance of our findings, we sought to correlate macroH2A1.1 isoform expression, and by extension TOP1cc repair capacity, with survival outcomes in cancer patients treated with TOP1cc trapping agents." (PMID 40796804, 2025). "This function has clinical implications for therapeutic regimen involving TOP1 inhibition and points to macroH2A1.1 as a predictive marker for cancer cell sensitivity to TOP1 poisons." (PMID 40796804, 2025).
cancer (continued). "We propose macroH2A1 alternative splicing as an epigenetic modulator of TOP1-associated genome maintenance and a potential cancer vulnerability." (PMID 40796804, 2025). "Functionally, these splicing factors potentially contribute to cancer cell migration and invasion through modulating the alternative splicing of macroH2A1." (PMID 34203934, 2021). "This pattern could be related to the macroH2A1 histone-linked epigenetic landscape and the biological clock’s ability to control the expression of metalloproteinases, which play a crucial role in inflammatory processes, extracellular matrix homeostasis, wound healing, and cancer cell migration." (PMID 34440260, 2021). "This permanent change in gene expression was associated with the ability of MYC to bind to specific promoter loci, suggesting a potential function for macroH2A1 in cancer development." (PMID 34203934, 2021). "The reduction in macroH2A1.1 is functionally important in cancer and it has effects on the proliferation and metastatic potential of cancer cells." (PMID 32974186, 2020). "MacroH2A1.2 indeed cooperates with epigenetic regulators to inhibit the expression of osteoclastogenic-promoting factors secreted by cancer cells." (PMID 33167489, 2020). "MacroH2A1 appears to act as tumour suppressor or as an oncogene depending on the type of cancer and on the degree of stemness." (PMID 32401230, 2020). "The cell cycle inhibitor p16 is another target gene of macroH2A1-dependent silencing in cancer cell lines but we still ignore if this contributes to regulating proliferation in primary tumors." (PMID 33167489, 2020). "Biased splicing towards the macroH2A1.2 isoform at the expense of macroH2A1.1 is reported in several cancer types, through downregulation of the QKI splicing factor, or through the activity of the DDX5 and DDX17 RNA helicases." (PMID 33167489, 2020). "MacroH2A1 has two splice isoforms, macroH2A1.1 and macroH2A1.2, that have been studied in several form of cancer." (PMID 32974186, 2020). "As opposing functions for H2AZ and MacroH2A1 in gene regulation were reported in cancer cells, we investigated the role of MacroH2A1.1 and MacroH2A1.2 isoforms in PCa development." (PMID 31164793, 2019). "Alterations in the expression of total MacroH2A1 or its isoforms has been observed in several cancer types, including breast carcinoma, melanoma, lung carcinoma and colorectal carcinoma." (PMID 31164793, 2019). "Taken the bulk literature together the MacroH2A1.1 isoform emerges as pleiotropic tumor suppressor, by repressing cell proliferation, migration and invasion, whereas the role of MacroH2A1.2 is largely cancer-type dependent." (PMID 31164793, 2019). "Further studies are now required to better understand the role of macroH2A1 proteins in cancer cell stemness." (PMID 31096699, 2019). "Current evidence also supports a tumor-suppressive role for macroH2A1.1, while the role of macroH2A1.2 is dependent on the specific cancer context." (PMID 31096699, 2019). "The relative level of macroH2A1.1 splicing is significantly perturbed across many types of cancer, resulting in reduced macroH2A1.1 expression." (PMID 30510186, 2018). "While current evidence clearly supports a tumour suppressive role for macroH2A1.1 and macroH2A2, the function of macroH2A1.2 seems to depend greatly on the context of the particular cancer studied." (PMID 29495465, 2018). "Concomitantly, the non-PAR binding macroH2A1.2 exhibited greater expression in several CRC lines, suggesting selection for increased macroH2A1.2 vs. macroH2A1.1 isoform splicing disparity in these cancers." (PMID 28934364, 2017). "Briefly, current data support a tumour-suppressive role for macroH2A1.1, whereas the function of macroH2A1.2 is dependent on the specific cancer context." (PMID 29206173, 2017). "Some of the switch factors controlling macroH2A1 splicing into macroH2A1.1 or macroH2A1.2 isoforms have been identified in cancer cells: QKI and RNA helicases Ddx17/Ddx5." (PMID 27800025, 2016).
cancer (continued). "MacroH2A1 isoforms regulate cancer cell growth in vitro and their expression levels have been shown to mark HCC, colon and lung cancer recurrence." (PMID 24473773, 2014). "In cancers with poor prognosis, alternative splicing of the H2AFY gene strongly favours macroH2A1.2 expression, due to decreased activity of the splicing factor QKI." (PMID 25003966, 2014). "Of note, macroH2A1.1 suppresses growth of cancer cells in a manner dependent on its ability to bind NAD+ metabolites such as OAADPR." (PMID 24473773, 2014). "Beyond cancer treatment, macroH2A1.1 may protect from repeated TOP1 cleavage, particularly at actively transcribed genes, which were recently shown to accumulate a unique TOP1 mutation signature that contributes to mutagenesis and malignant transformation." (PMID 40796804, 2025). "Hereby, they may remove active histone marks and establish a more condensed chromatin structure at the locus of macroH2A1 target genes to repress their transcription in cancer cells." (PMID 34203934, 2021). "MacroH2A1.1 acts as a tumour suppressor by inhibiting cell proliferation, migration, and invasion, while the function of MacroH2A1.2 is largely dependent on the type of cancer." (PMID 33858382, 2021). "Finally, regarding cancer-induced osteoclastogenesis, heterochromatin protein 1α (HP1α) and histone H1 protein (H1.2) were identified as major downstream effectors for macroH2A1.2-mediated oncogene suppression." (PMID 34203934, 2021). "One example of how cancer- and cell type-dependent interactions may influence cellular functions is the case of macroH2A1.1 and its capacity to bind poly ADP-ribosyl polymerase I (PARP-1)." (PMID 34203934, 2021). "Because the contribution of this histone variant to carcinogenesis has been reported in several cancer types, but not for PCa, we aimed to investigate the contribution of MacroH2A1 for prostate carcinogenesis." (PMID 31164793, 2019). "Importantly, macroH2A1.1 expression is often lost in cancer cells and transformed cell lines, explaining some of the disparate results regarding PARP1’s role in BER seen in the field." (PMID 31636161, 2019). "Among them, macroH2A1 is involved in stem cell reprogramming and cancer progression." (PMID 29339820, 2018). "Additionally, macroH2A1 plays a role in cancer biology, particularly in proliferation and metastasis." (PMID 29339820, 2018). "Moreover, macroH2A1 isoforms have recently taken center stage in the plasticity of stem cell differentiation and in the pathogenesis of many cancers, providing an exciting, yet poorly understood, link to metabolism and nutrients." (PMID 29206173, 2017). "The impact of macroH2A1 on transcriptional processes has now come to take a center stage in the plasticity of stem cell differentiation and in the pathogenesis of a growing number of cancer types." (PMID 27800025, 2016). "Recently, it has been shown that splicing of macroH2A1 isoforms regulates cancer cell growth." (PMID 23372727, 2013). "Moreover, our findings in cancer cell lines and TCGA patient samples suggest that macroH2A1.1 expression is predictive of TOP1cc repair capacity, which may ultimately help refine TOP1i treatment strategies." (PMID 40796804, 2025). "Once in the nucleosome, macroH2A1 may contribute to different cellular processes, including cell cycle regulation, stem cell differentiation, and DNA repair and transcription in somatic and cancer cells." (PMID 35331312, 2022). "In addition to misexpression, the splicing pattern of macroH2A1 is also altered in cancer cells." (PMID 33167489, 2020). "Our functional and immunological analyses on the macroH2A1-dependent CSC-like secretome suggest that this epigenetic pathway might provide an under-appreciated link between cancer stemness propagation in the tumor microenvironment (TME), and tumor-cell evasion from adaptive immune surveillance." (PMID 31903159, 2020).
cancer (continued). "Once in the nucleosome, macroH2A1 may contribute to different cellular processes, including cell cycle regulation, embryonic and adult stem cell differentiation, and DNA repair and transcription in somatic and cancer cells." (PMID 31096699, 2019). "Indeed, the role of the two MacroH2A1 isoforms have been investigated in cancer." (PMID 31164793, 2019). "macroH2A1 successfully altered the metabolism of carbohydrates and lipids in HCC cells to promote the transformation into cancer stem cells by increasing lipid accumulation via activation of the LXR pathway." (PMID 38921460, 2024). "Here, E3 ligase Skp2 was identified to mediate macroH2A1 ubiquitination and degradation, in turn promoting CDK8 gene and protein expression that contributed to cancer progression." (PMID 34203934, 2021). "MacroH2A1.1 is also a target for PARP1, which in turn is a common target for cancer drug development, because of PARP-1’s involvement in many cellular activities including DNA repair and transcription factor regulation." (PMID 26262644, 2015). "MacroH2A1.1 expression determines sensitivity to TOP1 poisons and may present a cancer vulnerability." (PMID 40796804, 2025). "Moreover, macroH2A1 was able to rewires carbohydrate and lipid metabolism of HCC cells towards cancer stem cells with increased lipid accumulation through activation of the LXR pathway." (PMID 35331312, 2022). "Furthermore, macroH2A1 was able to reprograms carbohydrate and lipid metabolism of HCC cells towards cancer stem cells with elevated lipid accumulation through triggering of the LXR pathway." (PMID 36612019, 2022). "MacroH2A1 KD is able to increase lipid synthesis and to activate glycolytic pathways and in particular the pentose phosphate pathway (PPP) in HCC cells, rewiring energy metabolism to the needs of a cancer stem cell (CSC)-like state." (PMID 32401230, 2020). "Endogenous macroH2A1 expression is lowly or not expressed in embryonic stem cells, iPSC and cancer stem cells." (PMID 29206173, 2017). "Finally, in cancer cells, a switch in the expression from PARP1-regulated macroH2A1.1 to PARP1-insensitive macroH2A1.2 is observed." (PMID 26262644, 2015). "MacroH2A1.1 but not macroH2A1.2 protects against the occurrence of various human cancers, influencing pathogenesis and/or survival." (PMID 24473773, 2014). "Given the role of EMT in metastasis, and macroH2A1.1’s role in inhibiting PARP-1 activity, our findings could provide insight into understanding EMT progression, and potentially provide a new mechanism as to how macroH2A1 expression affects cancer progression." (PMID 29339820, 2018). "This could be due to the fact that absence of macroH2A1 enhances stem like properties in cancer cells, as it is observed in the bladder and in the liver." (PMID 29206173, 2017). "Variations in macroH2A1 transcriptional activities to a large extent independent of genome occupancy in response to nutritional and DNA methylation status have been reported in cancer cells." (PMID 27800025, 2016). "Moreover, we found that FAK KD HepG2 and Huh-7 cells, but not macroH2A1 KD HepG2 and Huh-7 cells, displayed a simultaneous significant increase (p < 0.01) in the mRNA levels of cancer stemness suppressor genes GATA6, SMAD4, and BMP7, and of tumor-promoting genes KDR and SOX2." (PMID 33182805, 2020). "Moreover, guardians of genome stability involved in cancer such as SWItch/Sucrose non-fermentable (SWI/SNF) helicase, α-thalassemia/MR, X-linked (ATRX) and aprataxin-PNK-like factor (APLF) act as negative and positive regulators, respectively, of macroH2A1’s chromatin association." (PMID 29206173, 2017).
tumor (43 papers, 2014 to 2025). "Nuclear TRIM59 then promotes the tumor-suppressive histone variant macroH2A1 ubiquitination and degradation, leading to enhanced STAT3 signaling activation and tumorigenicity." (PMID 31488827, 2019). "On the other hand, tumor cells over-expressing macroH2A1.1 or macroH2A1.2 reached a smaller size compared to WT cells, supporting the idea that macroH2A1 expression is associated with HCC differentiation." (PMID 31096699, 2019). "The histone variant, macroH2A1, has an important role in embryonic stem cell differentiation and tumor progression in various types of tumors." (PMID 26028027, 2016). "Histone variant macroH2A1 (mH2A1) has been reported as a tumor suppressor." (PMID 39545415, 2024). "Finally, the attenuation of malignant phenotype of PCa cell lines after manipulation of Macro H2A1 expression, further suggest a tumor suppressor role for this histone variant, although MacroH2A1.1 and MacroH2A1.2’s role in PCa require further investigation." (PMID 31164793, 2019). "Therefore, while it is generally accepted that histones macroH2A1.1 and macroH2A2 act as tumour suppressors, macroH2A1.2 variant seems to be an oncogene associated with disease progression and negative patient outcome." (PMID 25003966, 2014). "Variants of the macroH2A family, like macroH2A1 (coded by H2AFY gene) and macroH2A2 (coded by H2AFY2 gene) regulate gene expression important for differentiation, stem cell reprogramming and tumor suppression." (PMID 40655151, 2025). "In most cases, macroH2A1.1 acts as a tumor suppressor, while macroH2A1.2 demonstrates a pro-tumorigenic role." (PMID 39199381, 2024). "QKI also regulates the alternative splicing of macroH2A1 pre-mRNA, thereby inhibiting tumor cell proliferation." (PMID 38782769, 2024). "For instance, QKI served as a tumor suppressor and inhibited gastric carcinogenesis via alternative splicing of the histone macroH2A1." (PMID 35614517, 2022). "In part, tumor suppressive functions of macroH2A1.1 can be explained by its capacity to bind and inhibit auto-modified PARP-1." (PMID 34203934, 2021). "In particular, MacroH2A1.1 is mostly considered a tumor suppressor, inhibiting stem cell-like properties and counteracting the functions of MacroH2A1.2." (PMID 31164793, 2019). "Nevertheless, MacroH2A1 downregulation is likely to play a role along prostate tumorigenesis, suggestive of a tumor suppressive effect." (PMID 31164793, 2019). "Overall, our data, derived from primary PCa tissues and cell lines, anticipate a tumor suppressive role for MacroH2A1, particularly for the MacroH2A1.1 isoform, in prostate carcinogenesis." (PMID 31164793, 2019). "By assaying HCC human samples by immunohistochemistry (IHC), we found a direct correlation between macroH2A1 expression and tumor differentiation." (PMID 31096699, 2019). "Possibly through its capacity to bind PARP-1, macroH2A1.1 positively regulates the level of tumour suppressive SOD3 and the gene expression program that supports paracrine senescence." (PMID 29495465, 2018). "A large amount of data highlighted the primarily tumor suppressive function of macroH2A1, which was reviewed elsewhere." (PMID 29206173, 2017). "In vitro, macroH2A1.1 reduction increases tumor cell growth and proliferation." (PMID 39199381, 2024). "Moreover, downregulation of miR-362-5p promoted the protein levels of QKI, MacroH2A1.1, PARP-1, p27 in tumor tissues, while reduced the protein levels of Cyclin D, MacroH2A1.2, c-Fos, and E2F1." (PMID 32194406, 2020). "Functional assays identified a tumor suppressive role for macroH2A1.1 in GC: Cyclin dependent kinase 8 (CDK8) expression analysis and wound healing assays showed that HGC-27 cells over-expressing macroH2A1.1 were less proliferative and invasive than control cells." (PMID 31096699, 2019). "Moreover, less differentiated and more aggressive PCa cases display lower QKI and MacroH2A1.1 transcripts levels, as expected for putative tumor suppressors." (PMID 31164793, 2019).